NOTCH1 (notch receptor 1)
Diseases named in the same sentence as NOTCH1 in open-access papers (continued):
Sharing a sentence is not in itself a finding about the gene and the disease.
glioma (continued). "In contrast, inhibiting p65 phosphorylation in glioma cells overexpressing PDGF‐D led to the downregulation of NOTCH1 and reversed EMT." (PMID 40530904, 2025). "Taken together, PDGF‐D promotes the EMT, migration, and invasion of glioma cells by activating NOTCH1 signaling." (PMID 40530904, 2025). "Brontictuzumab is a human monoclonal antibody that blocks NOTCH1 signaling and has already been proposed as a potential treatment for glioma and other cancers." (PMID 38601343, 2024). "Research has shown that both Notch1 and its ligands are highly expressed in numerous cell lines of glioma and primary human glioma." (PMID 38672496, 2024). "Thereupon, western blot analysis was further performed to confer the correlation between BRD4 and Notch1 protein expression after glioma cells were treated for 48 h." (PMID 39544152, 2024). "We found that after differential therapy the expression of CD133, Notch1, and Oct4 decreased in 8 cell cultures out of 10, which reflects the effect of the therapy on glioma stem cells." (PMID 38988707, 2024). "The potential antitumor effects of cannabinoids through the Notch1 signaling pathway were previously demonstrated in glioma, where THC induced the expression of p8 protein, upstream to ATF3/4." (PMID 39258755, 2024). "FOXD2-AS1 overexpression recruits TAF-1 to the promoter region of NOTCH1, resulting in upregulation of NOTCH1 and promotion of the stemness of gliomas." (PMID 38967893, 2024). "The effect of NOTCH1 down regulation, investigated on two glioma cell lines (U87MG and U251), was correlated with the reduction of GB proliferation." (PMID 37887005, 2023). "BRD4 was shown to be occupied at the Notch1 promoter site, thus controlling the Notch1 signaling pathway that is involved in regulating the self-renewal capacity of glioma stem cells and their tumorigenicity." (PMID 37628849, 2023). "The study demonstrated that ISL inhibited glioma stem cell proliferation as well as induced glioma stem cell differentiation via downregulating the Notch1 signaling." (PMID 37250146, 2023). "Exosomes from glioma stem cells (GSCs-exo) significantly promoted proliferation and invasion of glioma cells due to the highly enriched Notch1 protein in GSCs-exo." (PMID 37789353, 2023). "Inactivation of this pathway with y-secretase or Notch1 knockdown leads to inhibition of glioma stem-like cells into endothelial cells." (PMID 38203654, 2023). "Our previous work demonstrated that TRPM7 induces gliomagenesis and glioma stemness to promote glioma cell survival and invasion, where one of the mechanisms is through regulating its downstream Notch 1/Survivin pathway." (PMID 37642779, 2023). "β-1,4-GalT-V was also found to regulate Notch1 signaling in the trans-differentiation process of glioma stem-like cells into vascular endothelial cells; by decreasing the expression of β-1,4-GalT-V, Notch1 cleavage was reduced." (PMID 38203654, 2023). "The CD133+ CSCs isolated from the glioma cell line were susceptible to γ-secretase inhibitors (GSI), or Notch1/2 knockdown, compared to the respective CD133-negative glioma cells." (PMID 35205721, 2022). "RT‐qPCR and Western blot analysis depicted that NOTCH1 expression in glioma tissues was much higher than that in normal tissues." (PMID 35419917, 2022). "LncRNA FOXD2‐AS1 is upregulated in GSCs and glioma tissues, which helps to positively regulate NOTCH1 expression." (PMID 35419917, 2022).
glioma (continued). "The data showed that IPS reprogramming factors and pluripotency-related genes (POU5F1, SOX2, KLF4, MYC and NOTCH1) were detected in almost all histologic types and grades of gliomas." (PMID 36435765, 2022). "Elevated Dll1, Notch1, Notch3, Notch4, and HEY1 levels were associated with advanced glioma grade and poor prognosis, strongly suggesting that Notch signaling influences an undifferentiated and aggressive brain cancer phenotype." (PMID 36627893, 2022). "In this study, we used shRNA to inhibit the expression levels of Notch1 in glioma cells, and we revealed that EMT (N-cadherin decreased, E-cadherin increased) and the proliferation, migration, and invasion of cancer cells were significantly decreased." (PMID 36180477, 2022). "LncRNA FOXD2‐AS1, TAF‐1 and NOTCH1 were found to be elevated in glioma tissues and GSCs, and silencing lncRNA FOXD2‐AS1 inhibited stemness and proliferation, while promoting apoptosis and differentiation of GSCs." (PMID 35419917, 2022). "The analysis shows that Notch1 and Sox2 have a positive feedback regulation mechanism, and Notch4 predicts the malignant degree of glioma." (PMID 35935338, 2022). "Various studies have demonstrated increased expression of distinct components of Notch signaling pathway (such as Notch1, Notch2, Dll1, Dll4 and Jag1) and Notch target genes (Hey1, Hey2, Hes1) in glioma cell lines or primary human glioma samples including GBM." (PMID 36010607, 2022). "High expression of CXCR4 in glioma was modulated through Akt/mTOR signaling by Notch1, which promotes the migration of glioma-originating cells." (PMID 35571062, 2022). "To more fully discern the mechanism of miR-30c in gliomas and to clarify that miR-30c can inhibit the EMT process of gliomas by reducing the expression levels of Notch1, we implemented a cotransfection experiment." (PMID 36180477, 2022). "NF-κB activator protein in glioma modulates stromal cell-derived factor 1 and macrophage colony-priming factor by targeting Notch1." (PMID 35846128, 2022). "In our study, we aimed to explore the specific role of lncRNA FOXD2‐AS1 in the proliferation and differentiation of GSCs along with the relationship between lncRNA FOXD2‐AS1/TAF‐1/NOTCH1 signalling pathway in glioma." (PMID 35419917, 2022). "Further analysis indicated that overexpression of GAS5 in GSCs substantially diminished the expression of stem cell markers, including CD133 and Notch1, which are related to the stemness and malignant progression of gliomas." (PMID 36106122, 2022). "When the inhibitor was transfected into glioma cells, the expression levels of the Notch1, NICD, HES1 and HEY1 proteins in the inhibitor group were significantly higher than those in the inhibitor NC group (P < 0.05)." (PMID 36180477, 2022). "PlncRNA-1 overexpression induces glioma progression through boosting expressions of Notch1, JAG1 and Hes1, stimulating Notch signal." (PMID 36229883, 2022). "EGFR (21%), PTEN (17%), and NF1 (12%) mutations in the high-glioma risk score group and CIC (28%), FUBP1 (11%), and NOTCH1 (10%) mutations in the low-risk score group were identified, and the mutation frequency of these genes was greater than 10%." (PMID 36311792, 2022). "Autophagy regulates Notch1 degradation during the development of stem cells and neurogenesis and during the self-renewal of glioma-initiating cells and tumorigenicity." (PMID 36104669, 2022). "As Notch1 and Notch2 play a major role in the glioma tumorigenesis and in therapy resistance, we next examined the effects of X-rays and CII on the protein expression of NOTCH1 and NOTCH2 receptors." (PMID 36359750, 2022). "shRNA-Notch1 attenuated the enhancement effect of the inhibitor on EMT and the proliferation, migration, and invasion of glioma cells, thus confirming that miR-30c regulates these processes in glioma cells posttranscriptionally by targeting Notch1." (PMID 36180477, 2022).
glioma (continued). "Inactivating mutations in Notch pathway components, particularly in the NOTCH1 and NOTCH2 receptor and RBPJ genes, have been detected in isocitrate dehydrogenase (IDH) mutant gliomas." (PMID 36358826, 2022). "Based on the important role of Notch1, we were eager to determine which miRNA mainly regulates it in gliomas." (PMID 36180477, 2022). "For example, Notch1 promotes the migration and invasion of glioma cells by activation of β-catenin and NF-κB signaling via AKT." (PMID 35098869, 2022). "We found that NOTCH1 was expressed at higher levels in GSCs and glioma tissues, consistent with results in a prior study." (PMID 35419917, 2022). "Among the interacting mRNAs, the NOTCH1 gene’s role in glioma pathogenesis is well established as it affects glioma tumorigenesis and maintenance." (PMID 33926464, 2021). "It is now well-established that the activation of the Notch1 pathway antagonizes glioma proliferation." (PMID 34771555, 2021). "Notch1 expression positively correlates with glioma progression, and high expression of Notch1 is an independent predictor of low survival rates in patients with gliomas." (PMID 34804926, 2021). "For example, the highly expressed circNfix in glioma can act through the circNfix/miR-378e/RPN2 axis or be a sponge for miR-34a-5p and upregulate the target gene NOTCH1 to enhance glioma invasion through the Notch signaling pathway." (PMID 34745938, 2021). "Recently, it has been shown in vivo that NOTCH1 is an important modulator of TM-network formation in glioma cells." (PMID 34204510, 2021). "In contrast, hsa-miR-129-5p has been shown to inhibit the cell cycle and induce apoptosis in glioma cell lines through inhibition of NOTCH1 and mTOR signaling." (PMID 33926464, 2021). "Endothelial cells are known to activate NOTCH1 signaling in adjacent glioma cells, including glioma stem-like cells." (PMID 33579922, 2021). "Notch1 knockdown in glioma cells increases cell death, reduces proliferation and arrests the cell cycle; it also inhibits growth and invasion of GBM cells." (PMID 34804926, 2021). "Our evaluation of these two groups further confirms that SNHG6 as well as Notch1 are elevated in high grade gliomas and are thus verified targets for therapy." (PMID 34485294, 2021). "A similar role for Notch1 activation was also observed in isocitrate dehydrogenase 1 (IDH1) mutant diffuse low-grade gliomas." (PMID 34771555, 2021). "Another study indicated that β-elemene selectively inhibited the proliferation of glioma stem-like cells (GSLCs), including U87, U373, SHG-44, T98G, and SKMG-4 cells compared with parental glioma cells associated with downregulating Notch1 expression." (PMID 33801899, 2021). "Suppression of Notch1 impairs the proliferation and survival of glioma cell lines as well as human gliomas." (PMID 36643842, 2021). "In an extensive study on the functional role of NOTCH1 in gliomas, it is observed that NOTCH1 is involved in maintaining glioma cells in an undifferentiated state, and its inhibition leads to cells maturing into a less aggressive phenotype." (PMID 33926464, 2021). "The levels of SNHG6 and Notch1 were also found elevated in Grade IV glioma patients (n = 4) relative to Grade II glioma patients (n = 5)." (PMID 34485294, 2021). "Notch1 signaling plays an important role in cancer cell proliferation; HDAC5 was shown to promote Notch1 expression in glioma cells, leading to increased glioma cell proliferation." (PMID 34178647, 2021). "Noteworthy, NUMB exerts its major effect for maintaining normal neural and glioma stem cell state by inhibiting NOTCH1 signaling, which allows brain tumor growth and glioma stem cell proliferation." (PMID 31963852, 2020).
glioma (continued). "Notch1 loss-of-function mutations correlate with low-grade gliomas and have the best prognosis, in line with other studies where high expression of CSL, Notch1 or Notch2 sustains the tumor growth." (PMID 32796631, 2020). "The Notch1-mediated signaling pathway plays a crucial role in the maintenance of neural stem cells and is critical for glioma cell growth and progression." (PMID 32526957, 2020). "The Notch1 pathway has been revealed to sustain the stemness phenotype in glioma, which is consistent with our previous research." (PMID 33135348, 2020). "For example, the interference of Notch1 in glioma cells can promote the apoptosis, proliferation, and cell cycle arrest of glioma cells." (PMID 33014056, 2020). "Notch-1 overexpression correlates with a high grade glioma and a poor prognosis, suggesting that upregulated Notch-1 signaling promotes a more undifferentiated and aggressive tumor phenotype." (PMID 32998285, 2020). "In the current study, we first show that TRPM7-mediated Notch1 signaling activation is a crucial contributor to glioma cell proliferation and GSC stemness." (PMID 33381038, 2020). "Previous studies have shown that Notch-1 is upregulated in many glioma cell lines and primary human gliomas by promoting cell survival, proliferation, and invasion." (PMID 32998285, 2020). "Notch1 expression and activation contribute to glial cell transformation and glioma growth/survival, migration/invasion through Ras, β-catenin, NF-κB, AKT activation and downregulation of PTEN." (PMID 33381038, 2020). "Given this, we expect that the Notch1 signaling blockade will reverse the effects of TRPM7 on glioma proliferation." (PMID 33381038, 2020). "Positivity analysis of the stained samples demonstrated that the untreated glioma tumour samples had the highest amount of Notch1." (PMID 31863639, 2020). "Silencing of Notch1 can revert the effects of TRPM7 on cell cycle and programmed cell death in glioma cells, which indicates that Notch1 can replace the TRPM7 function, or TRPM7 functions through Notch1 signaling pathway." (PMID 33381038, 2020). "In glioma, NKAP can accelerate gliomas via Notch1 signaling and is considered an important oncogenic factor." (PMID 33553160, 2020). "In agreement with this, in vitro and xenotransplantation studies with glioma cell lines have indicated that CD133-positive GSCs are particularly sensitive to γ-secretase inhibitors (GSI) or NOTCH1/2 knockdown compared to CD133-negative glioma cells." (PMID 33076453, 2020). "Lastly, we determined the changes in TRPM7-mediated regulation of glioma cell growth/proliferation, cell cycle, and apoptosis by targeting Notch1." (PMID 33381038, 2020). "Similar to that in the TKO HCC model, in a delTP53 forebrain glioma tumor mouse, NOTCH1, NOTCH2, or RBJP knockout accelerates tumor progression, in part, by the downregulation of HES5." (PMID 33003595, 2020). "In vitro assays identified the expression of Notch1 and Notch4 receptors, with Notch1 being strongly expressed in low-grade gliomas and low in glioblastomas, whereas Notch4 is upregulated in glioblastoma and astrocytomas." (PMID 32796631, 2020). "Taken together, these results evidently suggested that NKAP together with Notch1 signaling was involved in regulation of the immune microenvironment of gliomas." (PMID 31277684, 2019). "In recent years, Notch1 has been found to be overexpressed in GICs, and the Notch pathway plays a vital role in the stem maintenance of glioma cells." (PMID 31382985, 2019). "For instance, a higher expression of ASCL1, Dll1, Notch1, -3, -4, and Hey1 correlates with a higher glioma grade and a worse prognosis, indicating that more activated Notch signaling promotes a more undifferentiated and aggressive tumor phenotype." (PMID 30832246, 2019). "In fact, upregulation of Notch1 sustains glioma stem cell phenotype, while autophagy induction counteracts such an effect by suppressing Notch1 signaling." (PMID 31387280, 2019).
glioma (continued). "The Notch1 signaling pathway proteins (Notch1, Hes1) were obviously elevated in high grade glioma tissues particularly in GBM tissues." (PMID 31382985, 2019). "Previous research has shown that Notch1 is upregulated in many glioma cell lines and primary human gliomas." (PMID 31277684, 2019). "HDAC5 is a histone deacetylase that enhances Notch1 expression in glioma cell lines promoting cell proliferation." (PMID 31628391, 2019). "Although NKAP inhibited the Notch1 downstream pathway in the immune system, our study revealed that it activated the Notch signaling in gliomas." (PMID 31277684, 2019). "Taken together, it is concluded that NKAP performs its oncogenic functions via Notch1 signaling, and this finding provides a novel perspective to find potential therapeutic targets for gliomas." (PMID 31277684, 2019). "By sponging miR-34a-5p via the Notch signaling pathway, another circRNA, circNFIX, was reported to regulate NOTCH1 to promote glioma progression." (PMID 30781524, 2019). "In this study, we provided the first evidence showing the functional roles of NKAP in gliomas by targeting Notch1 signaling." (PMID 31277684, 2019). "It is well established that Notch1 signaling plays a critical role in various human cancers including gliomas." (PMID 31277684, 2019). "In glioma cells, activation of Notch1 by DLL4 stimulation or overexpression of NICD induces AKT phosphorylation, promoting the migration and invasion of the cells." (PMID 31057403, 2019). "In glioma cells, Notch1 activation can induce AKT phosphorylation, facilitating the migration, and invasion." (PMID 31057403, 2019). "STC1, a secretory glycoprotein, is highly expressed in glioma spheres; it is able to bind Notch1 and activate the Notch1-SOX2 signaling pathway, therefore supporting the stemness and tumorigenicity of GSCs." (PMID 30832246, 2019). "NFIX circular RNA (circNFIX), which regulates NOTCH1 to promote glioma progression by sponging miR-34a-5p via the Notch signaling pathway, will be discussed in the latter portion of this review." (PMID 30781524, 2019). "The orthotopic GICs implantations were established to analyze the role and the mechanism of Notch1 in glioma progression in vivo." (PMID 31382985, 2019). "In particular, increased expression of Notch1 is correlated with increasing grades of glioma malignancy." (PMID 31277684, 2019). "The expression of NKAP and Notch1 in glioma and normal human brain samples were analyzed by immunohistochemical analysis." (PMID 31277684, 2019). "What’s more, we provided unequivocal evidence for the first time demonstrating that NKAP performed its function in part via regulating glioma immune microenvironment through targeting Notch1." (PMID 31277684, 2019). "Overall, our findings provided new insight into the regulatory relationship between NKAP and Notch1 in the tumorigenesis of gliomas." (PMID 31277684, 2019). "This suggests an alternative for multiple treatments of glioma by regulating the miR-139-5p/Notch1/EMT pathway." (PMID 30170559, 2018). "Given the central role of Notch1 signaling in glioma cells, Notch1-antagonizing strategies hold great promise in therapies of GBM." (PMID 29410396, 2018). "In this study, we investigate the association between two molecules involved in glioma neoangiogenesis, OPN and Notch-1, and two stem cell markers, nestin and CD133." (PMID 30140373, 2018). "Accordingly, we transfected miR-139-5p mimics into glioma cells and evaluated the Notch1 expression level." (PMID 30170559, 2018). "To confirm that GICs harbored elevated Notch1 activity, we established glioma neurospheres in vitro." (PMID 29410396, 2018).